ATP6V0C (ATPase H+ transporting V0 subunit c)
Description:
Proton-conducting pore forming subunit of the V0 complex of vacuolar(H+)-ATPase (V-ATPase), a multisubunit enzyme composed of a peripheral complex (V1) that hydrolyzes ATP and a membrane integral complex (V0) that translocates protons. V-ATPase is responsible for acidifying and maintaining the pH of intracellular compartments, and in some cell types, it is targeted to the plasma membrane, where it promotes acidification of the extracellular environment (By similarity). The V-ATPase complex also acts as an activator for mTORC1 on lysosomal membrane by promoting the guanine nucleotide exchange factor (GEF) of the Ragulator complex, thereby enabling mTORC1 recruitment.
Synonyms: ATP6C; ATP6L; ATPL; VATL; Vma3; EPEO3; VPPC
Tractability: Small molecule: a structure with a bound ligand is known. Antibody: its Gene Ontology location is reachable by antibodies, with high confidence; UniProt predicts a signal peptide or a membrane-spanning region. PROTAC: UniProt records ubiquitination sites on it; its protein half-life has been measured.
Gene: Protein-coding gene on chromosome 16 (2,513,713 to 2,520,218, forward strand). Ensembl gene ENSG00000185883.
Subcellular location: Cytoplasmic vesicle, clathrin-coated vesicle membrane; Cytoplasmic vesicle, secretory vesicle, synaptic vesicle membrane; Lysosome membrane
Subcellular location (Human Protein Atlas): Vesicles
Pathways (Reactome):
Immune System: Neutrophil degranulation; ROS and RNS production in phagocytes
Transport of small molecules: Ion channel transport; Transferrin endocytosis and recycling
Cellular responses to stimuli: Amino acids regulate mTORC1
Developmental Biology: Regulation of MITF-M-dependent genes involved in lysosome biogenesis and autophagy
Signal Transduction: Insulin receptor recycling
Gene Ontology:
Molecular function: guanyl nucleotide exchange factor activator activity; protein binding; ubiquitin protein ligase binding; proton-transporting ATP synthase activity, rotational mechanism; proton-transporting ATPase activity, rotational mechanism; proton transmembrane transporter activity
Biological process: cellular response to amino acid stimulus; positive regulation of TORC1 signaling; positive regulation of Wnt signaling pathway; endosomal lumen acidification; Golgi lumen acidification; intracellular pH reduction; lysosomal lumen acidification; proton transmembrane transport; regulation of macroautophagy; vacuolar acidification; proton motive force-driven ATP synthesis; synaptic vesicle lumen acidification
Cellular component: extracellular exosome; focal adhesion; lysosomal membrane; lysosomal proton-transporting V-type ATPase complex; membrane; azurophil granule membrane; endosome membrane; ficolin-1-rich granule membrane; Golgi membrane; phagocytic vesicle membrane; plasma membrane; proton-transporting V-type ATPase complex; tertiary granule membrane; vacuolar proton-transporting V-type ATPase, V0 domain; bounding membrane of organelle; clathrin-coated vesicle membrane; proton-transporting two-sector ATPase complex, proton-transporting domain; proton-transporting V-type ATPase, V0 domain; synaptic vesicle membrane
Genetic constraint (gnomAD): Loss-of-function variants: 2 observed, 8.52 expected, observed/expected ratio (o/e) 0.23, 90% interval 0.095 to 0.74. That is too few expected variants to judge how well the gene tolerates losing a copy. Missense variants: 89 observed, 202.18 expected, observed/expected ratio (o/e) 0.44, 90% interval 0.37 to 0.52. Synonymous variants: 128 observed, 99.07 expected, observed/expected ratio (o/e) 1.29, 90% interval 1.12 to 1.5.
Homologues: Orthologues: chimpanzee ATP6V0C (99% identical), dog ATP6V0C (97% identical), zebrafish atp6v0cb (92% identical), guinea pig ATP6V0C (92% identical), mouse Atp6v0c (91% identical), rat Atp6v0c (91% identical), zebrafish atp6v0ca (90% identical), rabbit ATP6V0C (86% identical), Drosophila melanogaster Vha16-1 (81% identical), Drosophila melanogaster Vha16-3 (77% identical), Drosophila melanogaster Vha16-2 (68% identical), Caenorhabditis elegans vha-2 (67% identical), and 2 more. Paralogues in human: ATP6V0B (34% identical).
Diseases named in the same sentence as ATP6V0C in open-access papers:
ATP6V0C is named in the same sentence as 15 diseases in open-access papers, as found by Europe PMC text mining. Sharing a sentence is not in itself a finding about the gene and the disease. The quoted sentences say what the papers report.
epilepsy (2 papers, 2023). A brain disorder characterized by episodes of abnormally increased neuronal discharge resulting in transient episodes of sensory or motor neurological dysfunction, or psychic dysfunction. "Many genes encoding subunits of V-ATPases, namely ATP6V0C, ATP6V1A, ATP6V0A1, and ATP6V1B2, have been associated with neurodevelopmental disorders and epilepsy." (PMID 37628590, 2023). "ATPase H+ transporting V0 subunit c (ATPV0C), encoding c-subunit of the vacuolar ATPase, is another human epilepsy driver gene, as it has been reported to cause intellectual impairment and epilepsy." (PMID 37047373, 2023).
COVID-19 (1 paper, 2022). A disease caused by infection with severe acute respiratory syndrome coronavirus 2. "Similarly, the ATP6V0C (c subunit) and ATP6V1F (F subunit) of V-ATPase also showed cell type-specific expression levels in moderate/severe COVID-19 patients." (PMID 35974012, 2022).
Flavivirus Infections (1 paper, 2012). Infections with viruses of the genus FLAVIVIRUS, family FLAVIVIRIDAE. "We also used a positive control siRNA, siV0C, which targets the transcript coding for ATP6V0C, a subunit of the V-ATPase complex previously shown to be required for flavivirus infection." (PMID 23029581, 2012).
melanoma (1 paper, 2021). A malignant, usually aggressive tumor composed of atypical, neoplastic melanocytes. "Furthermore, proteomic data analysis and western blot results showed the importance of the classical signaling pathways PI3K/Akt/FOXO and AMPK, and that new biological processes involve proteins such as ATP6V0C, CASP7, and PEX11B, which play crucial roles in USP7 mediating melanoma growth." (PMID 33869052, 2021).
cancer (5 papers, 2015 to 2023). A tumor composed of atypical neoplastic, often pleomorphic cells that invade other tissues. "ATP6V0C (Vacuolar ATPase c subunit) is a transmembrane protein that translocates protons between plasma membranes and plays a crucial role in extracellular microenvironment formation which is involved in invasion and metastasis of cancer." (PMID 35130884, 2022). "Thus, although it needs to be confirmed with further experiments, according to these data, it is possible to speculate that in our carcinoma models, oxygen tension similarly modulates ATP6V0C activity." (PMID 34124067, 2021). "The V-ATPase H+ transporting genes (ATP6V0D1, ATP6V0C, ATP6V0E1) maintain the intracellular pH and thus are critical for the Warburg effect observed in the cancer cells." (PMID 38114687, 2023).
ATP6V0C also shares sentences with these, for which no sentence is quoted: tumor (6 papers); hepatocellular carcinoma (4); breast carcinoma (2); colorectal cancer (2); Cirrhosis (1); glioblastoma (1); glioma (1); intellectual impairment (1); neurodegenerative disease (1); neurodevelopmental disorder (1).